ITIH5 (inter-alpha-trypsin inhibitor heavy chain 5)
Diseases named in the same sentence as ITIH5 in open-access papers (continued):
Sharing a sentence is not in itself a finding about the gene and the disease.
pancreatic cancer (12 papers, 2016 to 2024). "Our results indicate that loss of ITIH5 in pancreatic cancer profoundly affects its molecular profile: ITIH5 potentially interferes with a variety of oncogenic signaling pathways, including the PI3K/AKT pathway." (PMID 38375974, 2024). "These authors concluded that the presence of LINC00261 and GATA6 may impair the self-renewal and tumorigenesis capacity of pancreatic cancer stem cells, whereas the suppression of ITIH5 expression caused by LINC00261 downregulation rescued these tumorigenic functions." (PMID 35158755, 2022). "Inter-alpha-trypsin inhibitor heavy chain 5 (ITIH5) has been identified as a metastasis suppressor gene in pancreatic cancer." (PMID 38375974, 2024). "In many cancer entities like, e.g., breast, bladder and pancreatic cancer, it was described previously that ITIH5 represents a typical class II tumor suppressor gene being silenced by epigenetic promoter hypermethylation." (PMID 39518085, 2024). "Cellular effects, including cell migration, focal adhesion formation and protein tyrosine kinase activity, induced by forced ITIH5 expression in pancreatic cancer cell lines were studied in stable transfectants." (PMID 38375974, 2024). "Since then functionally studies revealed, for instance, ITIH5 mediated suppression of breast and pancreatic cancer metastases in vitro and in vivo." (PMID 32046186, 2020). "ITIH5 has been revealed as a potent metastasis suppressor in both breast and pancreatic cancer." (PMID 35158755, 2022). "Furthermore, by applying a genome-wide screen, Sasaki and colleagues identified ITIH5 as one of the few candidate genes that can strongly suppress pancreatic cancer metastasis." (PMID 35158755, 2022). "In pancreatic cancer, overexpression of ITIH5 inhibited cell motility and invasion, and ITIH5 variant without secretion signal decreased pancreatic cancer liver metastasis." (PMID 33935281, 2021). "To test our hypothesis that ITIH5 secretion would be required for suppression of pancreatic cancer metastasis, we first sought to characterise the intracellular localisation of ITIH5 in PDAC." (PMID 33024269, 2021). "In addition, ITIH5 was characterized as a putative metastasis suppressor gene in breast and pancreatic cancers." (PMID 32046186, 2020). "In pancreatic cancer stem cells, the long non-coding RNA (lncRNA) LINC00261 was suggested to bind to GATA6, increasing its activity at the ITIH5 promoter." (PMID 35158755, 2022). "ITIH5 impaired metastasis formation in pancreatic cancer cells in vivo but it did not affect their growth rates." (PMID 35158755, 2022). "Bearing in mind that ITIH5 did not impair the growth of pancreatic cancer cells, intracellularly acting ITIH5 proteins might be particularly responsible for the changes in cell plasticity." (PMID 35158755, 2022).
bladder cancer (9 papers, 2017 to 2024). "Facing the expression loss of ITIH5 in basal-type bladder cancers, we further aimed to analyze the functional impact of this tumor suppressor gene on basal-type bladder cancer cells in vitro." (PMID 33924987, 2021). "ITIH5 has previously been shown to be epigenetically silenced in various cancer entities, including bladder cancer, where its expression was associated with tumor recurrence of the clinical important group of high-grade pT1 patients." (PMID 32046186, 2020). "Loss of ITIH5 expression in breast and bladder cancer has been associated with clinical parameters of malignant progression and metastasis predicting poor prognosis in both entities." (PMID 28231808, 2017). "However, considering CD44, a basal-type marker but also a putative mediator of the HA-dependent function of ITIH5, we found a significant impact of ITIH5 on risk for recurrence only in bladder cancers with strong CD44 expression." (PMID 33924987, 2021). "In lung and bladder cancer cells, loss of ITIH5 was associated with unfavourable prognosis." (PMID 33935281, 2021). "Next, we aimed to assess the involvement of cancer progression-related biological processes and pathways in basal-type bladder cancer cells with squamous features potentially affected by the ITIH5-HA-CD44 axis." (PMID 33924987, 2021). "ITIH5 promoter methylation was also characterized as putative biomarker for non-invasive detection of breast and bladder cancer via plasma and urine samples, respectively." (PMID 33924987, 2021). "Next, we stained n = 52 bladder cancer tissues for ITIH5 and CD44 protein expression by immunohistochemistry." (PMID 33924987, 2021). "In conclusion, we gained insight into the tumor suppressive role of ITIH5 in (basal-type) bladder cancer demonstrating an impact on standard therapy approaches in vitro." (PMID 33924987, 2021). "Since 2004, ITIH5 has been reported to block tumor growth, migration and metastasis of various types including breast, pancreatic and bladder cancer." (PMID 33924987, 2021). "In 2014, the prognostic impact of the tumor suppressor ITIH5 has been studied in bladder cancer, however, its function in basal-type bladder cancer remained poorly understood." (PMID 33924987, 2021). "A cluster analysis of luminal and basal-type markers including ITIH5 expression revealed differences among intrinsic bladder cancer subtypes: Basal-type bladder cancers were characterized by abundant ITIH5 mRNA expression loss." (PMID 33924987, 2021). "In bladder carcinogenesis, the downregulation of ITIH5 was also associated with worse prognosis while functionally high-grade bladder cancer cells showed reduced growth in vitro after ITIH5 overexpression." (PMID 32046186, 2020). "As an example, the TIMP2 and ITIH5 genes showed decreased 5hmC in gene bodies in bladder cancer compared with the normal bladder samples, and hMeDip-qPCR/MeDip-qPCR verified the increase in 5hmC and a relative decrease in 5mC." (PMID 30005692, 2018). "Of clinical significance, we provide functional evidence that ITIH5 expression may support response of bladder cancers to chemotherapeutics." (PMID 33924987, 2021). "ITIH5 DNA methylation, which was shown to be useful as biomarker to detect bladder cancer via urine, may further hold information for predicting chemo-response of bladder cancer patients." (PMID 33924987, 2021). "Next, the biomarker quality of ECRG4 and ITIH5 promoter methylation was tested and then compared to a known putative bladder cancer methylation biomarker (NID2) by Methylation Sensitive Restriction Enzyme (MSRE) qPCR at the independent laboratories of Biotype GmbH (Dresden, Germany)." (PMID 32046186, 2020). "In the presented study, we focused on two putative tumor suppressor genes in bladder cancer that may also hold a prognostic impact, namely inter-α-trypsin inhibitor heavy chain 5 (ITIH5) and esophageal cancer-related gene 4 (ECRG4 or C2orf40)." (PMID 32046186, 2020).
bladder cancer (continued). "We now provide evidence that ECRG4 and ITIH5 DNA methylation could be useful as urinary biomarkers for non-invasive bladder cancer detection." (PMID 32046186, 2020). "Therefore, we aimed to characterize the two putative tumor suppressor genes ECRG4 and ITIH5 as novel urinary DNA methylation biomarkers that are suitable for non-invasive detection of bladder cancer." (PMID 32046186, 2020). "However, this is consistent with our recent finding in luminal-like RT112 bladder cancer cells due to ITIH5 re-expression." (PMID 28231808, 2017). "Interestingly, the patient group with high ITIH5 expression still demonstrates a favorable overall survival, like in tumor entities such as breast and bladder cancer, where ITIH5 is clearly downregulated in the tumor, compared to their normal tissue counterparts." (PMID 39518085, 2024). "Thus, ITIH5 might be of interest to develop novel panels of predictive biomarkers helping to stratify bladder cancer patients for (neo)adjuvant treatment." (PMID 33924987, 2021). "Stable single-cell clones were generated using a full-length ITIH5 cDNA pBK-CMV expression vector (pBK-ITIH5 clones) or empty vector (pBK-mock clones) based on the basal-type, SCC-like bladder cancer cell line SCaBER (SC clones) and HT1376 (HT clones)." (PMID 33924987, 2021). "Contrary to that, basal-type HT1376 bladder cancer cells overexpressing ITIH5 did not alter short-term cell growth." (PMID 33924987, 2021). "Hence, ITIH5 and, in particular, ECRG4 might be promising candidates for further optimizing current bladder cancer biomarker panels and platforms." (PMID 32046186, 2020).
colon cancer (6 papers, 2013 to 2024). "In serum samples from patients with colon cancer, DKK3 was detected in seven (22.6%) of 31, whereas ITIH5 was present in nine (29%) of 31 cases." (PMID 23320751, 2013). "Considering all control samples, including sera from patients with colon cancer, benign breast disease, and healthy controls, yielded a specificity of 93% (139 of 149) with combined DKK3 and ITIH5 methylation." (PMID 23320751, 2013). "ITIH5 is also expressed by normal skin fibroblasts but not by epidermal keratinocytes and is a novel putative tumour suppressor gene in colon cancer." (PMID 30678366, 2019).
lung carcinoma (5 papers, 2017 to 2022). "Based on an integrated genomic and transcriptomic approach Wu and colleagues recently demonstrated rare somatic ITIH5 gene mutations in lung cancer whose frequency increased up to 6% in corresponding metastases." (PMID 28231808, 2017). "ITIH5 has been shown to be an effective tumor and metastasis suppressor which is being lost in various tumor entities including breast, bladder and lung cancer." (PMID 35158755, 2022). "Truncated ITIH5 variants caused dose-dependent cell growth inhibition by up to 50% when applied to various cancer cell lines (e.g., MDA-MB-231, SCaBER, A549) reflecting breast, bladder and lung cancer in vitro." (PMID 35158755, 2022).
melanoma (5 papers, 2021 to 2025). A malignant, usually aggressive tumor composed of atypical, neoplastic melanocytes. "Loss of ITIH5 was related to the metastasis and progression of melanoma." (PMID 33935281, 2021). "In addition, reduced ITIH5 expression was associated with the staging of melanoma." (PMID 33935281, 2021). "Second, overexpression of ITIH5 suppressed melanoma metastasis and tumorigenesis in vitro and ex vivo." (PMID 33935281, 2021). "In this study, we demonstrated that the mRNA and protein levels of ITIH5 were decreased in melanoma tissues compared with normal skin tissues." (PMID 33935281, 2021). "Forced expression of ITIH5 significantly inhibited melanoma cell proliferation and metastasis in vitro and ex vivo while knockdown of ITIH5 expression enhanced the malignant behaviour of melanoma cells." (PMID 33935281, 2021). "To confirm the tumour-suppressive role of ITIH5 in melanoma, we first examined the expression of ITIH5 in 40 formalin-fixed and paraffin-embedded melanocytic tumours and 40 normal skin tissues by IHC staining of TMAs." (PMID 33935281, 2021). "Taken together, these data strongly suggest that ITIH5 is an important tumour suppressor in melanoma whose expression levels are positively correlated with overall survival rates of melanoma patients." (PMID 33935281, 2021). "First, the expression levels of ITIH5 were significantly downregulated in melanoma tissues compared with normal skin tissues." (PMID 33935281, 2021). "In vitro and ex vivo, enhanced ITIH5 expression significantly inhibited the growth and metastasis of melanoma cells." (PMID 33935281, 2021). "To better understand the role of ITIH5 in melanoma cells, we subsequently investigated the effects of ITIH5 on tumour growth and metastasis ex vivo." (PMID 33935281, 2021). "In this study, we showed that ITIH5 expression was markedly reduced in melanoma tissues compared with normal skin tissues." (PMID 33935281, 2021). "Overall, these data suggest that ITIH5 is a bona fide inhibitor of tumour growth and metastasis in melanoma." (PMID 33935281, 2021). "The IHC results showed that the expression of ITIH5 in metastatic melanoma was reduced as compared with that in primary melanoma." (PMID 33935281, 2021).
melanoma (continued). "In the Transwell cell migration assay, the extent of migration of ITIH5-overexpressing melanoma cells was remarkably lower than that of control cells." (PMID 33935281, 2021). "To evaluate the contribution of ITIH5 to the development of human melanoma, we first detected the expression levels of ITIH5 in a panel of six melanoma cell lines by western blotting and RT-qPCR." (PMID 33935281, 2021). "Although these data suggest that ITIH5 is a key tumour-suppressor gene in various cancers, its role and the regulatory mechanism are still unclear in melanoma." (PMID 33935281, 2021). "Here, we found that the expression of ITIH5 was decreased in melanoma tissues compared with normal skin tissues." (PMID 33935281, 2021). "Decreased expression of ITIH5 was correlated with clinicopathological features and predicted poor prognosis in patients with melanoma." (PMID 33935281, 2021). "ITIH5 reportedly inhibits the growth and metastasis of melanoma in humans." (PMID 40229704, 2025). "In addition, we also found that melanoma patients with relatively low ITIH5 levels showed lower survival rates than patients with high ITIH5 levels in the tumours." (PMID 33935281, 2021). "Increased ITIH5 expression inhibited melanoma cell growth and metastasis in vitro and ex vivo." (PMID 33935281, 2021). "We therefore wanted to determine whether ITIH5 suppresses melanoma malignancy by downregulating KLF4." (PMID 33935281, 2021). "However, depletion of ITIH5 expression accelerated melanoma progression." (PMID 33935281, 2021). "We found that ITIH5 overexpression significantly suppressed cell proliferation and migration in KLF4 wild-type melanoma cells." (PMID 33935281, 2021). "Based on this, we assessed the effect of ITIH5 on the expression of NUCB2, a known target gene of KLF4, in melanoma cells." (PMID 33935281, 2021). "Unexpectedly, we found that overexpression or knockdown of ITIH5 did not change KLF4 protein levels in melanoma." (PMID 33935281, 2021). "We found that the expression of ITIH5 in melanoma tissues was significantly lower than that in normal skin tissues." (PMID 33935281, 2021). "In addition, our data demonstrated that ITIH5 was a bona fide interacting protein of KLF4 that suppressed the transcriptional activity of KLF4 and downregulated its target gene NUCB2, leading to the suppression of melanoma." (PMID 33935281, 2021).
melanoma (continued). "To understand the potential molecular mechanism of the suppressive effect of ITIH5 on KLF4-mediated melanoma progression, we first evaluated the protein levels of KLF4 in melanoma cells with or without ITIH5 knockdown or overexpression." (PMID 33935281, 2021).
Obesity (5 papers, 2012 to 2024). Accumulation of substantial excess body fat. "ITIH5 may also be a regulator of human metabolism, as the expression of ITIH5 in adipose tissue was increased in obesity, and associated with measures of body size and metabolism." (PMID 23285140, 2012). "Based on these findings, ITIH5 has been proposed as a potential novel target for controlling or modulating adipose tissue homeostasis to counteract the development of obesity and related metabolic disorders." (PMID 39198923, 2024). "Increased expression of ITIH-5 in adipose tissue in obesity seems to be a direct link between obesity and LE aggravation." (PMID 33923324, 2021). "Based on these findings, ITIH5 was originally proposed as a novel marker of obesity." (PMID 39198923, 2024). "Thus, ITIH5 has been proposed to be an inert marker of human obesity." (PMID 39198923, 2024). "CNTNAP2, GLI2, DPT (dermatopontin), AEBP1, ITIH5, CXCL11, GDNF (glial cell derived neurotrophic factor), MCHR1, FLT3, ELANE (elastase, neutrophil expressed), OSMR (oncostatin M receptor) and IL15RA are involved in development of obesity, but these genes might be key for progression of HF." (PMID 34218797, 2021).
cervical cancer (3 papers, 2021 to 2025). A primary or metastatic malignant neoplasm involving the cervix. "A study utilizing microarray-based expression analysis found that ITIH5 mRNA levels were significantly lower in cervical cancers compared to high-grade precursor lesions (CIN3), suggesting a role for ITIH5 in cervical carcinogenesis." (PMID 40508156, 2025).